FAM236D (family with sequence similarity 236 member D)
Gene: Protein-coding gene on chromosome X (72,807,425 to 72,808,210, reverse strand). Ensembl gene ENSG00000225396.
Homologues: Orthologues: mouse Fam236e (37% identical), rat Fam236d (37% identical), mouse Fam236f (35% identical). Paralogues in human: FAM236C (100% identical), FAM236A (91% identical), FAM236B (91% identical).